ZFYVE16 (zinc finger FYVE-type containing 16)
Description:
May be involved in regulating membrane trafficking in the endosomal pathway. Overexpression induces endosome aggregation. Required to target TOM1 to endosomes.
Synonyms: KIAA0305; PPP1R69
Tractability: Antibody: UniProt places it where antibodies can reach, with high confidence. PROTAC: ubiquitination databases record sites on it; its protein half-life has been measured.
Gene: Protein-coding gene on chromosome 5 (80,407,149 to 80,483,379, forward strand). Ensembl gene ENSG00000039319.
Subcellular location: Cytoplasm; Early endosome membrane
Subcellular location (Human Protein Atlas): Cytosol; Vesicles
Pathways (Reactome):
Signal Transduction: Signaling by BMP
Gene Ontology:
Molecular function: 1-phosphatidylinositol binding; phosphatidylinositol-3,4,5-trisphosphate binding; protein binding; metal ion binding
Biological process: endosomal transport; protein targeting to lysosome; regulation of endocytosis; signal transduction; vesicle organization
Cellular component: cytosol; early endosome; early endosome membrane; cytoplasm
Genetic constraint (gnomAD): Loss-of-function variants: 76 observed, 123.58 expected, observed/expected ratio (o/e) 0.62, 90% interval 0.51 to 0.74. The upper end of that interval is the gene's LOEUF score, 0.74, which puts it in group 3 of 6, group 1 being the genes least tolerant of losing a copy. Missense variants: 1,699 observed, 1,779.5 expected, observed/expected ratio (o/e) 0.95, 90% interval 0.92 to 0.99. Synonymous variants: 574 observed, 626.1 expected, observed/expected ratio (o/e) 0.92, 90% interval 0.86 to 0.98.
Homologues: Orthologues: chimpanzee ZFYVE16 (98% identical), macaque ZFYVE16 (94% identical), dog ZFYVE16 (85% identical), pig ZFYVE16 (83% identical), rabbit ZFYVE16 (73% identical), Drosophila melanogaster CG6051 (4% identical), Caenorhabditis elegans lst-2 (4% identical), Drosophila melanogaster CG31064 (4% identical), tropical clawed frog zfyve28a (4% identical), zebrafish plekhf1 (3% identical). Paralogues in human: ZFYVE26 (15% identical), PLEKHM2 (5% identical), ZFYVE28 (5% identical), RUFY1 (4% identical), PLEKHF1 (4% identical), PLEKHF2 (4% identical), RUFY2 (4% identical), ZFYVE1 (4% identical), RUFY3 (3% identical), SNX29 (3% identical), ZFYVE19 (3% identical), RUNDC3A (3% identical), and 1 more.
Diseases named in the same sentence as ZFYVE16 in open-access papers:
ZFYVE16 is named in the same sentence as 15 diseases in open-access papers, as found by Europe PMC text mining. Sharing a sentence is not in itself a finding about the gene and the disease. The quoted sentences say what the papers report.
gastric cancer (1 paper, 2016). A primary or metastatic malignant neoplasm involving the stomach. "The effects of somatic mutations in genes encoding zinc finger proteins (ZNF721 and ZFYVE16), a purine and pyrimidine metabolism protein (NT5E), carbonic anhydrase(CA1), and cyclic nucleotide phosphodiesterase(PDE10A)on the progress of gastric cancer requires further study." (PMID 27270314, 2016).
ovarian carcinoma (1 paper, 2024). A malignant neoplasm originating from the surface ovarian epithelium. "We found that a low expression level of CDKN2B and WNT11 was associated with longer survival in ovarian cancer patients, while high expression levels of SMAD3, ZFYVE16, BMP6, LEFTY1, and DVL2 were significantly associated with poor survival." (PMID 38403634, 2024).
pulmonary fibrosis (1 paper, 2023). Chronic progressive interstitial lung disorder characterized by the replacement of the lung tissue by connective tissue, leading to progressive dyspnea, respiratory failure, or right heart failure. "Compared with the control group, the BLM-induced pulmonary fibrosis group exhibited significantly higher expression of Fmod and Tgfbr2 mRNA; in contrast, the mRNA expression levels of Bambi, Skp1, Zfyve9, Zfyve16, Ppp2ca, Ppp2r1a, Ppp2r1b, Rps6kb1, and Rps6kb2 were markedly lower." (PMID 38259493, 2023).
ZFYVE16 also shares sentences with these, for which no sentence is quoted: cancer (2 papers); tumor (2); basal cell carcinoma (1); brain arteriovenous malformation (1); congenital heart disease (1); corneal dystrophy (1); gastroenteritis (1); hyper-IgE syndrome (1); Immunodeficiency (1); neurodevelopmental disorder (1); osteoporosis (1); psoriasis (1).